ZNF835 (zinc finger protein 835)
Description:
May be involved in transcriptional regulation.
Synonyms: BC37295_3
Tractability: No criterion of Open Targets' tractability assessment is met for any kind of drug.
Gene: Protein-coding gene on chromosome 19 (56,661,980 to 56,671,783, reverse strand). Ensembl gene ENSG00000127903.
Subcellular location: Nucleus
Subcellular location (Human Protein Atlas): Microtubules; Basal body; Cytokinetic bridge; Mitotic spindle; Primary cilium
Gene Ontology:
Molecular function: protein binding; DNA-binding transcription factor activity; RNA polymerase II cis-regulatory region sequence-specific DNA binding
Biological process: regulation of transcription by RNA polymerase II
Cellular component: nucleus
Genetic constraint (gnomAD): Loss-of-function variants: 0 observed, 0.38 expected, observed/expected ratio (o/e) 0, 90% interval 0 to 1.85. That is too few expected variants to judge how well the gene tolerates losing a copy. Missense variants: 783 observed, 777.23 expected, observed/expected ratio (o/e) 1.01, 90% interval 0.95 to 1.07. Synonymous variants: 323 observed, 333.12 expected, observed/expected ratio (o/e) 0.97, 90% interval 0.88 to 1.06.
Homologues: Orthologues: chimpanzee ZNF835 (99% identical), macaque ZNF835 (92% identical). Paralogues in human: ZNF16 (44% identical), ZNF189 (44% identical), ZNF568 (44% identical), ZNF7 (43% identical), ZNF658 (43% identical), ZFP28 (43% identical), ZNF33B (43% identical), ZNF629 (43% identical), ZNF605 (43% identical), ZNF470 (43% identical), ZNF484 (43% identical), ZNF229 (42% identical), and 164 more.
Diseases named in the same sentence as ZNF835 in open-access papers:
ZNF835 is named in the same sentence as 3 diseases in open-access papers, as found by Europe PMC text mining. Sharing a sentence is not in itself a finding about the gene and the disease. The quoted sentences say what the papers report.
colorectal cancer (1 paper, 2020). A primary or metastatic malignant neoplasm that affects the colon or rectum. "Differentially expressed ZNF835 was associated with ethnicity in colorectal cancer patients." (PMID 32190687, 2020).
glioblastoma (1 paper, 2023). The most malignant astrocytic tumor (WHO grade IV). "To investigate whether these genes with H4K5acK8ac-preferred promoters regulate glioblastoma stem-like properties, i. e., marker gene expression for stem cells and sphere formation efficiency, we disrupted ZNF883, RFX4, KLF11, and ZNF835 by siRNA knockdown in 0316-GSC cells." (PMID 37759202, 2023).
carcinoma (1 paper, 2021). A malignant tumor arising from epithelial cells. "The remaining signature genes, CPXM2, ENPP5, SAMD13, SLC52A1, ZNF682, ZNF835, ZNF571-AS1 and U91328.1, have not been related to carcinoma, yet." (PMID 33672117, 2021).